STAT3 (signal transducer and activator of transcription 3)
Diseases named in the same sentence as STAT3 in open-access papers (continued):
Sharing a sentence is not in itself a finding about the gene and the disease.
gastric cancer (continued). "We have now shown that forced expression of STAT3-CA attenuated PHA-665752-induced apoptosis in cells with MET activation, indicating that inhibition of STAT3 activity has a role in MET-TKI-induced apoptosis in MET-activated gastric cancer cells." (PMID 21730976, 2011). "Similar to the effects of PHA-665752, transfection with a siRNA specific for MET mRNA resulted in inhibition of STAT3 phosphorylation in gastric cancer cells with MET activation but not in MKN1 or MKN7 cells." (PMID 21730976, 2011). "This clinical observation was supported by mechanistic studies in gastric cancer cell lines, tumor organoids, and xenograft models, demonstrating that sildenafil suppresses tumor growth by inhibiting PDE5, destabilizing c-MYC, and downregulating IL-6/JAK/STAT3 signaling." (PMID 41450924, 2025). "In the colorectal cancer microenvironment, circPOLQ acts as a miR‐379‐3p sponge to counteract STAT3 inhibition, promoting CD206+ M2 macrophage infiltration—a mechanism functionally complementary to the circATP8A1/miR‐1‐3p/Hippo/STAT6 axis observed in gastric cancer." (PMID 41360672, 2025). "However, the mechanisms by which the p-STAT3/PIAS3 pathway regulates the occurrence and development of gastric cancer remain unclear." (PMID 36672337, 2023). "Moreover, gastric cancer cells treated with palmitic acid decreased the expression of p-STAT3, p-JAK2, N-cadherin and vimentin indicating that palmitic acid inhibited the growth of gastric cancer by blocking the STAT3 signaling pathway." (PMID 37240342, 2023). "Collectively, evodiamine inhibits growth of gastric cancer cells by inducing apoptosis, which might be mediated by activation of caspases and inhibition of mitochondrial apoptosis-related proteins, the FAK/AKT/mTOR pathway, and STAT3 signaling." (PMID 36135210, 2022). "However, the ectopic effect of terphenyllin on STAT3 and the actual target have not been verified in gastric cancer." (PMID 35401187, 2022). "STAT3 has been previously identified as an oncogene in gastric cancer from non-scRNAseq studies." (PMID 35757757, 2022). "Our previous study found that β2-AR could activate STAT3 and initiate EMT in gastric cancer cells." (PMID 35517411, 2022). "In conclusion, this study shows that marine-derived natural product terphenyllin binds to STAT3 inhibits the growth and metastasis of gastric cancer at an effective dose without significant toxicity in vitro and in vivo by inhibiting the STAT3 signaling pathway." (PMID 35401187, 2022). "GSDMD reduces the expression of Cyclin A2 and Cyclin-Dependent Kinase (CDK2) by inhibiting ERK1/2, STAT3, and PI3K/Akt in gastric cancer (GC) cells." (PMID 35963853, 2022). "The bioinformatic-based approach was further employed to analyze STAT3 expression on multiple tumors, indicating gastric cancer (GC), TNBC, and cervical cancer (CC) with high STAT3 expression." (PMID 36509291, 2022). "However, the role of STAT3 in neuronal related gene methylation in gastric cancer has never been explored." (PMID 33886682, 2021). "In research focused on gastric cancer (GC), the use of SIRT1 activator resveratrol (RSV) resulted in a significant reduction in STAT3 and c-myc gene expression as well as the expression of phosphorylated (STAT3-P) and acetylated (STAT3-Ac) forms of STAT3." (PMID 34769241, 2021). "miRNA (miR)-23a promotes EMT in lung and gastric cancer cells by inhibiting the expression of E-cadherin, whereas miR-193a-3p, miR-210-3p, and miR-5100 promote cancer cell invasion by activating EMT through the signal transducer and activator of transcription 3 (STAT3) pathway." (PMID 34485600, 2021). "Targeted inhibition of STAT3 may not be appropriate in gastric cancer patients with promoter hypermethylation of C11orf87." (PMID 33886682, 2021). "However, the role of JAK/STAT3 signaling on epigenetic silencing of tumor suppressive miR-193a in gastric cancer has never been explored." (PMID 33718136, 2021).
gastric cancer (continued). "In human gastric cancer (GC), HOXD-AS1 silencing inhibits cancer cell growth through inactivating janus kinase 2/signal transducer and activator of transcription 3 (JAK2/STAT3)." (PMID 32425696, 2020). "VEGF expression is increased by STAT3 activation through lincRNAs PVT1 and FLANC and hence, angiogenesis rises in gastric cancer (GC) and CRC, respectively." (PMID 32992718, 2020). "The reconstitution of TFF1 levels in TFF1-KO gastric gland organoids and human gastric cancer cells, significantly decreased the phosphorylation and nuclear localization of STAT3 with reduced expression of several known STAT3 target genes, further establishing a link between TFF1 and STAT3." (PMID 31292446, 2019). "However, as reported for gastric cancer, TAMs are capable of silencing TSG gelsolin in cancer cells by increased DNMT1 expression and DNA methylation of gelsolin promoter via activation of CCL5/CCR5/STAT3 signaling." (PMID 30200265, 2018). "Indeed, STAT3 plays a pivotal role in gastric carcinogenesis and progression, and induces epithelial-mesenchymal transition (EMT) by upregulation of mesenchymal transcription factors such as Snail1 in gastric cancer cells." (PMID 29409467, 2018). "Since direct inhibition of STAT3 is technically difficult and is limited in clinical efficacy, modulation of the SHP-1/STAT3 axis might be a promising therapeutic strategy in the treatment of gastric cancer, especially in overcoming chemoresistance." (PMID 29409467, 2018). "Although STAT3 may not be the direct target of SIRT1 in gastric cancer, combinatorial high expression of both these proteins can predict the worst survival outcome." (PMID 28061480, 2017). "Recent work reported that overexpression of miR-18a could promote cell proliferation in gastric cancer by regulating PIAS3 expression and consequentially increase STAT3 activity, leading to enhanced activation of genes downstream of STAT3 modulated by CASC2-targeting miRNAs." (PMID 27198161, 2016). "It is therefore necessary to further determine other upstream activators of the STAT3/Twist1/EMT pathway in the CMTM3-knockdown system and to investigate the function of CMTM3 on the expression, stabilization, internalization and degradation of RTKs in gastric cancer cells." (PMID 27121055, 2016). "We therefore conclude that ponicidin exhibited significant growth inhibition of gastric carcinoma cell line MKN28 and induced apoptosis of MKN28 cells via the signaling pathway regulated by Janus kinase 2 (JAK2) and signal transducers and activators of transcription 3 (STAT3)." (PMID 25588213, 2015). "Emerging evidence suggests that STAT3 activation can induce epithelial-mesenchymal transition and consequently propagate cancer stem cells (CSCs) that have been described to be responsible for HER2-targeting drug resistance and ultimate tumor recurrence in breast and gastric cancers." (PMID 25327561, 2014). "Moreover, transfection of dominant negative STAT3 or inhibition of STAT3 by AG490 in human gastric cancer cell lines resulted in reduced cell growth." (PMID 25594045, 2014). "We also performed an immunohistochemical analysis of phosphorylated STAT3 in 5 cases of Helicobacter pylori–negative healthy control, 5 cases of Helicobacter pylori–positive gastritis, 5 cases of gastric adenoma, and 5 cases of gastric cancer." (PMID 23593346, 2013). "Regarding the relationship between AFP production and STAT3 expression, there is no available report describing the underlying mechanisms to date.It has been reported that the AFP expression in gastric cancer is due to the lack of the transcription factor ATBF1." (PMID 23382965, 2013). "Therefore, a calpain/SHP-1-regulated STAT-3 and VEGF pathway may be involved in the angiogenesis, growth, and peritoneal dissemination of gastric cancer cells." (PMID 22937084, 2012).
gastric cancer (continued). "STAT3 and c-Jun could physically interact and bind to the AP-1 site, implicating that the interplay of both transcriptional factors on the AP-1 site is responsible for isoproterenol-stimulated MMP-7 expression in gastric cancer cells." (PMID 20939893, 2010). "Recent studies also found that blockade of STAT3 activity by the expression of the dominant-negative STAT3 can inhibit growth of AGS gastric cancer cell line, thus further suggesting that JAK/STAT may play an important role in development of gastric cancer." (PMID 15354212, 2004). "Furthermore, recent studies suggest that STAT3 inhibition may induce ferroptosis in certain (e.g. gastric cancer), but not all (e.g. pancreatic ductal adenocarcinoma) cancer types." (PMID 40743845, 2025). "In gastric cancer (GC), activation of JAK2/STAT3 could promote HIF-1α/VEGFA axis, and bolsters macrophage polarization, thus facilitating GC metastasis and angiogenesis." (PMID 39130627, 2024). "In addition, Calmodulin2 (CALM2) has been found to exhibit high expression in gastric cancer (GC) cells, modulating the JAK2/STAT3/HIF-1/VEGFA axis, promoting macrophage polarization, and facilitating ECs angiogenesis." (PMID 37666809, 2023). "Here, we report on the anti-EMT effect of ATO in gastric cancer cells by demonstrating dephosphorylation of JAK2/STAT3 and modulation of EMT markers including Snail1 and E-cadherin by ATO, and suggest that SHP-1 might be an important mediator for inactivation of the JAK2/STAT3 signaling pathway." (PMID 29409467, 2018). "Therefore, we hypothesized that STAT3 may not be a direct target of SIRT1 in our cohort of gastric cancer patients." (PMID 28061480, 2017). "Signal transducer and activator of transcription 3 activation by various receptor tyrosine kinases has previously been shown to be JAK dependent or JAK independent; however, it is unclear whether STAT3 is phosphorylated through JAK in MET-activated gastric cancer cell lines." (PMID 21730976, 2011). "Interestingly, STAT3 and c-Jun were found to bind to the single AP-1 site in MMP-7 promoter simultaneously, implicating that the interplay of both transcriptional factors at one binding site is responsible for isoproterenol-stimulated MMP-7 expression in gastric cancer cells." (PMID 20939893, 2010). "In gastric cancer microenvironments, SERPINE1 activates the JAK2/STAT3 pathway to promote exosomal packaging of let‐7g‐5p, which suppresses SOCS7 to relieve STAT3 negative feedback, driving STAT3 hyperphosphorylation and M2 polarization." (PMID 41360672, 2025). "Activation of STAT3 induced by H. pylori infection was shown to promote gastric oncogenesis, but the role of BMP1 in gastric cancer has not been examined before." (PMID 29720137, 2018). "On the other hand, we found that gastric cancer cells in which STAT3 is activated in the absence of MET activation secreted IL-6, and this cytokine then activated STAT3 through the JAK pathway." (PMID 21730976, 2011). "Furthermore, no study has shown that blocking STAT3 signaling in DZN + PNR affects the invasion, and development of gastric cancer cells." (PMID 40217305, 2025). "In gastric cancer patients, STAT3 can bind to the consensus DNA response elements within the promoters of NR-related genes (GPX4, SLC7A11, and FTH1) and promote the expression of these ferroptosis-negative regulators, thereby establishing a negative STAT3–ferroptosis regulatory axis (Bottom left)." (PMID 41513612, 2026). "Additionally, gastric cancer‐derived lncRNA MIR4435‐2HG is delivered via exosomes to interact with the Jagged1 intracellular domain, inhibiting Notch/Hes1 signaling and blocking JAK1/STAT3 negative feedback regulation, thereby promoting IL‐10 secretion." (PMID 41360672, 2025).
gastric cancer (continued). "Curcumin’s inhibitory effects on gastric cancer in experimental animals were also shown to be dependent not only on HIF-1α/VEGF decrease (shown immunohistochemically), but also on decrease of STAT3 (Signal Transducer and Activator of Transcription 3) transcription factor." (PMID 30857125, 2019). "We showed that isoproterenol-induced MMP-7 promoter activation was not disrupted by the mutagenesis of the core-sequences of all three STAT3 sites, suggesting that the STAT3 elements may not act in isoproterenol-induced MMP-7 gene transcription in gastric cancer cells." (PMID 20939893, 2010).
prostate carcinoma (714 papers, 2004 to 2026). A carcinoma that arises from epithelial cells of the prostate gland. "A reduction in STAT3 signaling in a prostate cancer mouse model has been associated with an increased likelihood of metastasis and disease recurrence." (PMID 40166646, 2025). "Abnormally expressed NCAPD3 in prostate cancer caused STAT3 to be highly expressed and bound to the promoters of JAK2 and EZH2 to promote their transcription, increasing the level of AKT phosphorylation, and accelerating tumor development." (PMID 39917394, 2025). "For instance, JAK2 has been associated with tumor mutational burden in prostate cancer, and STAT3 is recognized as a pivotal regulator in inflammatory and tumor signaling networks." (PMID 40978029, 2025). "Reduced expression or mutations in SOCS1 and SOCS3 have been associated with sustained STAT3 activation, accelerating the progression of pancreatic ductal adenocarcinoma, prostate cancer, and glioblastoma." (PMID 40166646, 2025). "The oncogenic transcriptional factor STAT3 that is upregulated in prostate cancer and melanoma, is also closely associated with inflammation." (PMID 39376605, 2024). "STAT-3 over expressions associated with proliferative markers are highly observed in prostate cancer models." (PMID 39574470, 2024). "The results demonstrated that NCAPD3 promoted tumor growth in prostate cancer through down-regulating miR-30a-5p, which was associated with the regulation of STAT3, MYC, and EZH2." (PMID 38561330, 2024). "Reduced expression or mutation of SOCS1 and SOCS3 causes constitutive STAT3 activation, which accelerates the progression of pancreatic ductal adenocarcinoma, prostate cancer, glioblastoma." (PMID 38245798, 2024). "Abnormal STAT3 activation in prostate cancer cells is linked to EGF receptor and JAK kinase-mediated trafficking of IL-6 and IL-11 cytokines." (PMID 36852795, 2023). "Aberrant STAT3 activity is linked to a wide variety of solid and hematologic malignancies, including colon, lung, and prostate cancers, and is most often caused by disruptions in cytokine signaling." (PMID 36852795, 2023). "Angiogenin expression has been associated with STAT3 signalling in prostate cancer and with HIF-1α in oral cancer." (PMID 37896150, 2023). "This study also demonstrated that consistent activation of STAT3 at the Y705 site conferred in prostate cancer cells a differentiated epithelial morphology, and that STAT3 loss induced a mesenchymal-like phenotype and higher tumor cell aggressiveness." (PMID 37190183, 2023). "On the other hand, studies on breast and prostate cancer have reported that a high p-STAT3 expression was associated with a favorable prognosis." (PMID 35314590, 2022). "After topological enrichment, the most connected upregulated genes MYC, CDK1, CCNB1 etc. and the most connected downregulated genes EGFR, VEGFA, STAT3 etc. were categorized according to their highest degree count associated with prostate cancer." (PMID 35456461, 2022). "The transcription factor signal transducer and activator of transcription 3 (STAT3) has been associated with aggressive tumor growth, reduced androgen sensitivity and metastatic spread in prostate cancer." (PMID 35917644, 2022). "An association between activated STAT3 with integrin b6 promoter, another marker of epithelial ovarian cancer progression, has been shown to promote tumorigenesis in prostate cancer." (PMID 36585738, 2022). "As another example, lncAMPC activates LIF/LIFR/Jak1/STAT3 pathway to stable PD-L1 and metastasis-associated genes, thereby contributing to metastasis and immunosuppression in prostate cancer." (PMID 33665192, 2021).